PPARG (peroxisome proliferator activated receptor gamma)
Diseases named in the same sentence as PPARG in open-access papers (continued):
Sharing a sentence is not in itself a finding about the gene and the disease.
pancreatic cancer (continued). "It appears that the subset of pancreatic cancers with the higher expression of PPARγ constitutes a more aggressive group and thus research on the regulation of this transcription factor in pancreatic cancer may present an opportunity for defining targets and eventually better treatments." (PMID 23049538, 2012). "Pancreatic cancer cells also showed enhanced activity of several PDAC-specific regulons, including PPARG, KLF3, FOXL1, MAFK and GLI2, and several regulons shared with squamous cells, such as TP63, FOSL1 and ELK3." (PMID 37914932, 2023). "Li et al16 have reported that activation of PPARγ can up‐regulate the tumour suppressor gene PTEN, thereby inhibiting the expression of MMP‐2, thus impairing the migration and invasion of pancreatic cancer cell lines." (PMID 33164330, 2020). "A PPARγ agonist, TGZ, showed cytotoxicity in two pancreatic cancer cell lines in a PPARγ-independent manner." (PMID 28673319, 2017). "PSF expression affected the expression of PPARγ, and knockdown of PSF using specific small-interfering RNA (siRNA) significantly suppressed the proliferation of pancreatic cancer cells." (PMID 26309807, 2015). "In order to corroborate previous findings, we then analyzed PPARγ, DNMT1, and 3B mRNA levels in four different pancreatic cancer cell lines." (PMID 22919364, 2012). "In this study we aimed to evaluate the expression of PPARγ, DNMT1, and DNMT3B and their correlation with clinical-pathological features in patients with pancreatic cancer (PC), and to define the effect of PPARγ activation on DNMTs expression in PC cell lines." (PMID 22919364, 2012). "Our current study identified the change of exosome and lipid metabolism-related genes with clinical value, and the 7-gene (ABCB1, CAP1, EGFR, ITGB1, MAPK1, PPARG, SNCA) prognostic formula is a novel and reliable predictive index in pancreatic cancer and other multiple cancers." (PMID 37857015, 2023). "Mechanisms for PPARγ control of the cell cycle involving upregulation of p18 and p21 during adipogenesis or increased p27 but not p21 in pancreatic cancer have also been reported." (PMID 22194735, 2011). "Furthermore, the combination of activating PPARγ and inhibition of COX2 expression has recently been shown to inhibit proliferation and induce apoptosis in pancreatic cancer." (PMID 19296839, 2009). "Ourown studies, employing two separate commercially available antibodies, showthat PPARγ is expressed in pancreatic cancer, but that expression in the cancercells does not appear to be different from that in normal pancreatic ductal cells." (PMID 19190780, 2008). "In our study, we found that PPARγ might diminish the PDAC stemness via decreasing the expression level of CD44 and CD133 in pancreatic cancer cells, enhancing the killing effect of Gemcitabine on pancreatic cancer cells." (PMID 35186942, 2021). "As PPARγ agonist thiazolidinediones have been shown to regulate growth and survival in a number of cancer cell lines, we designed this study to evaluate the antitumor effects of TGZ on pancreatic cancer cells in vitro and in vivo, and investigated its mechanism of cytotoxicity." (PMID 28673319, 2017). "In the present study, we investigated whether the PPARγ agonist, TGZ, exhibited in vitro cytotoxicity against two human pancreatic cancer cell lines, and clarified its mechanisms in terms of PPARγ dependency, apoptosis, and the mitogen-activated protein kinase (MAPK) pathway." (PMID 28673319, 2017). "Therefore, we concluded that the cytotoxic effect of TGZ in pancreatic cancer cells was independent of PPARγ activation." (PMID 28673319, 2017). "These suggest that the role of 15-keto-PGE2 specifically in the regulation of antioxidative signaling through xCT and CTH may not require PPARγ in pancreatic cancer cells." (PMID 26820738, 2016).
pancreatic cancer (continued). "Our data put in evidence important differences in the periodicity and in the phase relationships of PPARG, DNMT1, and DNMT3B expression levels among the diverse cell lines examined, maybe related to a different genetic background in the diverse pancreatic cancer cells." (PMID 22966223, 2012). "Recently, a study reporetd that Lipitor promoted human monocyte differentiation toward alternative M2 macrophages via p38 MAPK-dependent PPARγ activation in vitro,envn if, in that study, the M2 was not induced by pancreatic cancer, it could be also a strong support to our findings in this paper." (PMID 26879926, 2016). "Moreover, there are no reports concerning PPARγ dependency and in vivo antitumor efficacy of TGZ in pancreatic cancer cells, although PGZ was evaluated using an in vivo model." (PMID 28673319, 2017).
Glucose intolerance (58 papers, 2007 to 2026). Glucose intolerance (GI) can be defined as dysglycemia that comprises both prediabetes and diabetes. "Conversely, deletion of genes encoding transcription factors such as PPARγ that promote the alternative activation of M2 macrophages predisposes lean mice to the development of glucose intolerance and insulin resistance." (PMID 28440284, 2017). "Beta-cell specific PPARγ knockout mice exhibit glucose intolerance, impaired GSIS and deficiency in basal Pdx1 expression, as well as loss of sensitivity to the pharmacological effect of TZDs in enhancing Pdx1 expression." (PMID 23424659, 2013). "Collectively, our data provide the first evidence that ERβ-deficiency protects against diet-induced IR and glucose intolerance which involves an augmented PPARγ signaling in adipose tissue." (PMID 18584035, 2008). "Third, PPARβ deficiency led to increased PPARγ expression in vivo and in vitro, increased differentiation of MSCs into adipocytes, and increased bone marrow adiposity, thereby providing a new mechanism to explain the reduced bone formation in relation to glucose intolerance and lipid accumulation." (PMID 25279796, 2014). "MLN4924 injection improves high-fat diet (HFD)-induced glucose intolerance via inhibiting the neddylation of peroxisome proliferator-activated receptor gamma (PPARγ) in mouse models." (PMID 38212312, 2024). "In terms of mechanisms, deletion of IRF3 can increase the expression of PPARγ, leading to severe IR and glucose intolerance." (PMID 37303813, 2023). "PPARγ is a key factor for maintaining insulin sensitivity, and EVs from proinflammatory macrophages induce glucose intolerance and IR by disrupting PPARγ signaling." (PMID 33116121, 2020). "Together these results indicated LFE reduced body weight gains and improved glucose intolerance, possibly via PPARγ antagonism, and that its effects were more significant in subcutaneous adipose tissues." (PMID 27176632, 2016). "A recent mouse study demonstrated that genetic overexpression of preadipocyte PPARγ in the early postnatal period is protective against the development of glucose intolerance later in life, providing evidence that the regulation of preadipocyte PPARγ is worthy of mechanistic investigation." (PMID 40198135, 2025). "As opposed to IRF3, TAZ could protect mice from HFD‐induced IR and glucose intolerance through upregulating the expression of PPARγ." (PMID 37303813, 2023). "Moreover, GSDMD deficiency causes a mild increase in glucose intolerance and adiposity when challenged with a HFD, partly by regulating the expression of peroxisome proliferator-activated receptor gamma (PPARγ)." (PMID 36065376, 2022). "PAR4-/- mice developed less visceral adiposity and glucose intolerance under HFD, featuring smaller adipocytes, fewer macrophages and lower expression of adipogenic (leptin, PPARγ) and pro-inflammatory genes (CCL2, IL-1β) in WAT." (PMID 38652276, 2024). "PPARγ agonist treatment in OLETF rats resulted in fat redistribution with a decreasing V/S ratio and improved glucose intolerance." (PMID 26894429, 2016). "Studies have shown that regular-chow-diet-fed mice do not experience lipoatrophy or glucose intolerance despite the absence of PPARγ." (PMID 38276299, 2024). "The HFD mice develop glucose intolerance within a week that coincided with reduction in expression of SetD7 along with previously reported decreased expression of MafA, Glut2, Gck, GIPR, and PPARγ in islets." (PMID 34592314, 2021). "AT2 receptor activation is reported to induce PPARγ activation in PC12W cells, leading us to hypothesize that AT2 receptor-mediated improvement of glucose intolerance is at least in part due to PPARγ activation." (PMID 23155382, 2012). "Further in vivo evidence for molecular interaction of PPARγ and SetD7 was obtained using a pancreas-specific (PANC) PPARγ−/− knockout mouse that we previously characterized and observed to display glucose intolerance, but no change in β-cell mass." (PMID 34592314, 2021).
Cognitive impairment (57 papers, 2010 to 2026). Abnormal cognition is characterized by deficits in thinking, reasoning, or remembering. "This was confirmed by a PPARγ antagonist, which reduced microglial phagocytosis, suggesting PPARγ's role in synaptic loss and cognitive impairment." (PMID 41355958, 2026). "In summary, this study provides compelling evidence that CdCl2-induced hippocampal damage and cognitive impairments are closely associated with the downregulation of PPARγ, a critical regulator of oxidative stress, inflammation, and apoptosis in the brain." (PMID 40430476, 2025). "In several studies, the PPARG rs1801282 SNP was identified to be associated with insulin sensitivity and cognitive impairment." (PMID 28225792, 2017). "One proposed mechanism for the actions of PPARγ is that the anti-inflammatory effects of PPARγ linked to cognitive impairment." (PMID 27594837, 2016). "It has been demonstrated that the adiponectin/peroxisome proliferator-activated receptor gamma (PPARγ) axis is crucial for mitigating cognitive impairments resulting from chronic hypoperfusion." (PMID 41302488, 2025). "Beyond its role in metabolic regulation, PPARγ serves as a neuroprotective agent capable of attenuating cognitive deficits and neural damage in a variety of animal models of neurodegenerative diseases." (PMID 40430476, 2025). "High-intensity interval training (HIIT) can avert cognitive deficits by influencing PPARG gene expression, potentially forestalling cognitive impairment [PMID: 36503461]." (PMID 40766923, 2025). "PPARG’s involvement in cognitive impairment and its potential as a therapeutic target necessitate further investigation." (PMID 40766923, 2025). "We found that PA improved cognitive impairment, reduced the over production of proinflammatory cytokines, increased the expression of PPARγ, and inhibited the activation of the NF‐κB signaling pathway in AD model mice and Aβ‐stimulated BV2 microglia." (PMID 38421141, 2024). "In particular, the use of the PPARγ agonist rosiglitazone in a lithium–pilocarpine model of TLE was found to prevent cognitive impairment, increase antioxidant superoxide dismutase activity in brain cells, and reduce the inflammatory response of microglia." (PMID 37176158, 2023). "Thiazolidinedione (TZD) treatment with pioglitazone has also improved cognitive impairment in T2DM by activating peroxisome proliferator-activated receptor gamma (PPAR-γ)." (PMID 38082288, 2023). "In conclusion, LPD ameliorated cognitive deficits by enhancing brain glucose uptake through activation of PPARγ-dependent mitophagy in APP/PS1 mice." (PMID 36217155, 2022). "In docking analysis, 4-hydroxycinnamic acid and scopoletin showed the highest binding affinity to PPARγ, suggesting that these compounds can ameliorate cognitive deficits through activating PPARγ signaling." (PMID 36225186, 2022). "In APP/PS1 mouse model, TRPML1 has been reported to alleviate cognitive impairment in AD by mediating neuron autophagy and reducing autophagosome accumulation through the PPARγ/AMPK/mTOR signaling pathway." (PMID 35116093, 2022). "Here, we provide evidence that LPD is a novel PPARγ agonist and ameliorates cognitive deficits through PPARγ-dependent enhancement of mitophagy and glucose metabolism in the hippocampus of APP/PS1 mice." (PMID 36217155, 2022). "PPARγ agonists, including rosiglitazone and pioglitazone, have shown beneficial effects on cognitive deficits in transgenic mouse models of AD." (PMID 36217155, 2022). "The administration of PPARg agonists prevent radiation-induced toxicity and cognitive impairment in animal models." (PMID 33986314, 2021). "We demonstrated that PPARγ agonism with RSG alleviated a somewhat narrow range of hippocampus‐dependent cognitive deficits that rely upon dorsal hippocampus." (PMID 33382528, 2021).
Cognitive impairment (continued). "Oral administration of the PPARγ agonist pioglitazone, before, during or following fractionated WB irradiation (40 Gy) significantly improved cognitive impairment relative to untreated irradiated rats." (PMID 31936195, 2020). "Under pathological conditions, for instance under an inflammatory insult, PPARγ activation can restore neurogenesis and cognitive impairment." (PMID 30899454, 2019). "Recently, the focus of PPARγ in neural degenerative diseases has intensified, and many PPARγ ligands have been proposed as therapeutic approaches for the resulting cognitive impairment." (PMID 31614739, 2019). "Administration of PPARα agonist fenofibrate preserved hippocampal neurogenesis and prevented radiation-induced cognitive impairment; the application of pioglitazone, the PPARγ agonist, significantly recovered cognitive impairment in irradiated rats." (PMID 31450566, 2019). "Telmisartan, a unique ARB with PPARγ-stimulating activity, has been shown to counteract cognitive impairment through the up-regulation of BDNF/TrkB in the hippocampus, partially due to its ability to activate PPARγ." (PMID 31614739, 2019). "That these parameters were restored by PPARγ activation emphasizes the therapeutic value of RSG against early AD cognitive impairment." (PMID 25540218, 2015). "Although studies have not examined if PPARδ agonists can modulate radiation-induced cognitive impairment, data demonstrate that PPARγ can ameliorate or prevent radiation-induced cognitive decline." (PMID 22135673, 2011). "It is important to investigate if, similar to PPARγ, PPARδ can modulate radiation-induced cognitive impairment." (PMID 22135673, 2011). "SAR, however, markedly diminished the duration spent in one square, indicating an anxiolytic effect mediated by PPARγ’s capacity to inhibit pro-inflammatory cytokines like TNF-α and IL-6, which are implicated in neuroinflammation-related anxiety and cognitive impairment." (PMID 40863337, 2025). "In summary, LPD could increase brain glucose metabolism and ameliorate cognitive deficits through PPARγ-dependent enhancement of mitophagy in APP/PS1 mice." (PMID 36217155, 2022). "More recently, studies have shown that activation of adiponectin receptor with adipoRon could boost PPARγ expression and inhibit pro-inflammatory microglia responses, therefore ameliorating hyperperfused cognitive deficits." (PMID 35720361, 2022). "The ligands for PPARγ, including the thiazolidinedione class of antidiabetic drugs, could reverse cognitive deficits in rodent models of AD." (PMID 36217155, 2022). "PPARγ agonists such as fenofibrate, icariin, and naringenin are known to be neuroprotective, supporting neuronal development, synaptic plasticity, and ameliorating cognitive deficits." (PMID 36225186, 2022). "Previous study revealed that PPARγ depletion could promote oxidative stress injury in brain, and IH could induce oxidative stress in hippocampus, resulting in mice’s cognitive deficits." (PMID 34035184, 2021). "The results collected so far from in vitro and in vivo models highlight the positive effects of PPARγ agonists in ameliorating cognitive performances in AD, and propose these drugs, or natural ligands of PPARγ, as future therapeutic approaches in cognitive impairment." (PMID 31614739, 2019). "In the Tg2576 animal model for AD amyloidosis, activation of the peroxisome proliferator-activated receptor-gamma (PPARγ) with rosiglitazone (RSG) ameliorates hippocampus-dependent cognitive impairment and restores aberrant synaptic activity at the entorhinal cortex to DG granule neuron inputs." (PMID 25540218, 2015). "Similarly, although pioglitazone reduces tissue loss and cognitive impairment after TBI by PPARγ activation, this drug reduces microglial activation via a PPARγ-independent mechanism." (PMID 24215544, 2013).
Cognitive impairment (continued). "Similarly, pioglitazone (PIO), a peroxisome proliferator-activated receptor-gamma (PPAR-γ) agonist, and low-dose aspirin significantly reduced pro-inflammatory cytokines, with aspirin mitigating cancer-induced cognitive impairment by targeting tumor-derived inflammatory signaling." (PMID 41155372, 2025). "Overall, PPARγ has a wide spectrum of functions in nerve inflammation, energy metabolism, cerebrovascular protection, and reducing oxidative stress, which may significantly improve AD-induced cognitive impairment." (PMID 35535155, 2022). "Thus, both PPARγ agonists and ARBs may prevent/ameliorate radiation-induced cognitive impairment when given for only a few weeks after fWBI." (PMID 22833841, 2012). "The key findings of the current study are that 3xTgAD mice display cognitive deficits and impaired synaptic plasticity that can be rescued by AU9 through activation of PPARδ and partially PPARγ." (PMID 37190025, 2023). "Together, these findings suggested that ICS II attenuates CCH-induced cognitive deficits by inhibiting the amyloidogenic pathway via involvement of BDNF/TrkB/CREB signaling and up-regulation of PPARα and PPARγ in rats." (PMID 30405422, 2018). "Several DM hyperglycemia ameliorating drugs such as the peroxisome proliferator-activated receptor gamma (PPARγ) agonist, glucagon-like peptide-1 (GLP-1) and dipeptidylpeptidase-4 inhibitor were reported to improve the cognitive deficits in DM patients." (PMID 28489581, 2017). "Prakash and Kumar further found that a PPARγ agonist (pioglitazone), but not the antagonist bisphenol A diglycidyl ether (BADGE), protects Wistar rats from the cognitive impairments caused by Aβ injection." (PMID 30383537, 2018). "Moreover, treatment with another PPARγ agonist, pioglitazone, attenuates the production of Aβ plaque burden and glial inflammation in the APPV717I transgenic mice and cognitive impairments in AD patients." (PMID 28449688, 2017). "A promising therapeutic strategy for early AD cognitive impairment is treatment with the thiazolidinediones pioglitazone and rosiglitazone (RSG), potent and selective agonists of peroxisome proliferator-activated receptor-gamma (PPARγ)." (PMID 25540218, 2015). "Furthermore, the modulating effect of TCA on BACE1 levels was associated with the upregulation of PPARγ, SIRT1, and PGC1α, negative regulators of BACE1 that ultimately led to the improvement in cognitive impairment without any effects in the WT mice." (PMID 32599846, 2020). "The data clearly demonstrated that ICS II might produce protective effect against BCCAO-induced cognitive impairment by up-regulating the expressions of PPARα and PPARγ, not by retarding the decrease of the expressions of PPARα and PPARγ." (PMID 30405422, 2018).